CCN1 (cellular communication network factor 1)
Diseases named in the same sentence as CCN1 in open-access papers (continued):
Sharing a sentence is not in itself a finding about the gene and the disease.
myeloma (5 papers, 2014 to 2021). "This also proved that CCN1 do have stimulation on the osteoblasts of myeloma patients through PI3K/AKT‐GSK3β pathway." (PMID 31769620, 2020). "To investigate the possible involvement of PI3K‐AKT signal pathway in the CCN1 stimulating effect on osteoblasts, we first test our osteoblasts samples from both myeloma patients and healthy donors by PI3K‐AKT specific intracellular signaling antibody array." (PMID 31769620, 2020). "So we first collected several samples including the healthy donors and the myeloma patients, incubated with medium or CCN1 and then tested by the intracellular signaling antibody array." (PMID 31769620, 2020). "According to these results, we suppose that PI3K/AKT signal pathway has involvement in the CCN1 stimulation on osteoblasts, especially for the myeloma patients." (PMID 31769620, 2020). "In the present study, we investigated the expression of CCN1 in myeloma cells under conditions of a tumor-supportive microenvironment." (PMID 24965524, 2014). "We describe for the first time that myeloma cells display intron retention in CCN1 mRNA, followed by splicing of all introns, enhanced transcription and consecutive translation upon contact with MSC." (PMID 24965524, 2014). "We also demonstrate that this effect can be exerted by recombinant CCN1 protein which further enhances myeloma cell viability." (PMID 24965524, 2014). "We observed CCN1 intron splicing in INA-6 myeloma cells for all four introns of the CCN1 mRNA and enhanced transcription of CCN1 after co-culture with MSC." (PMID 24965524, 2014). "In the present study, we expand knowledge on regulatory mechanisms involving splicing of the proangiogenic, matricellular growth and differentiation factor CCN1/CYR61 in the tumor microenvironment with a special focus on myeloma-MSC interaction." (PMID 24965524, 2014). "We propose that contact with MSC-derived CCN1 leads to splicing and enhanced transcription of CCN1 which further contributes to the translation of angiogenic factor CCN1 in myeloma cells, supporting tumor viability and myeloma bone disease." (PMID 24965524, 2014). "We further performed blocking experiments with anti-integrin β1, β2, β3, β7 antibodies, as these integrins are described as being expressed on myeloma cells, and integrins α6β1 and αMβ2, which interact with the CT-domain of CCN1." (PMID 24965524, 2014). "Taken together, we show that INA-6 myeloma cells are able to produce functional CCN1 protein after MSC contact, which is induced by a splicing event concerning all introns as well as enhanced transcription." (PMID 24965524, 2014). "CCN1 is up regulated in multiple myeloma tissues as well as in patients’ sera." (PMID 34228239, 2021). "Because PTEN, 4E‐BP1, and PI3K‐AKT are popular protein targets involved in diverse of cancers, there might be concerns that whether CCN1 would increase the possibility of myeloma progression." (PMID 31769620, 2020). "Production of CCN1 by myeloma cells in addition to CCN1 derived from cells in the bone marrow may further lead to an angiogenic switch that is associated with disease progression." (PMID 24965524, 2014). "Our new findings include mechanistic data on the role of intron retention and splicing as a means of translation regulation of immediate early proteins of the CCN family as well as putative biological functions of CCN1 as a factor promoting myeloma cell viability." (PMID 24965524, 2014). "We conclude that CCN1 protein, delivered in a paracrine manner, is an appropriate stimulus to initiate complete splicing of intron-retaining CCN1 mRNA in myeloma cells, which further leads to protein translation in the target cell, maintaining further CCN1 expression in an autocrine manner." (PMID 24965524, 2014). "Thus CCN1 has the potential to be another method to treat myeloma bone disease." (PMID 31769620, 2020).
myeloma (continued). "Blocking antibodies targeting β-integrins (β1, β2, β3, and β7) that are relevant in myeloma, as well as αvβ3, the RGD-sensitive integrin comprised in CT domain, were unable to prevent the splicing induction of CCN1 mRNA by CCN1-Fc stimulation." (PMID 24965524, 2014). "To elucidate the role of CCN1 in the crosstalk between stromal cells and myeloma tumor cells, we performed co-culture experiments with primary MSC and the interleukin-6 (IL-6)-dependent myeloma cell line INA-6." (PMID 24965524, 2014). "We next wanted to investigate whether CCN1, as a MSC-derived factor, has a positive effect on myeloma cell viability." (PMID 24965524, 2014). "To elucidate the role of CCN1 in the crosstalk between stromal cells and myeloma cells, we performed co-culture experiments with primary mesenchymal stem cells (MSC) and the interleukin-6 (IL-6)-dependent myeloma cell line INA-6." (PMID 24965524, 2014). "We were able to detect a significantly increased cell viability of myeloma cells after CCN1 incubation independent of IL-6 suggesting CCN1 as a microenvironment-derived pro-myeloma factor." (PMID 24965524, 2014). "This study suggests that increasing CCN1 levels in the BM microenvironment may offer an approach to delay the progression of MGUS/SMM to active MM, as well as enhancing survival of patients with active myeloma." (PMID 27485291, 2016). "In the case of co-culture with MSC, myeloma cells survive independent of the IL-6/gp130/STAT3 pathway suggesting that other pro-myeloma factors, such as CCN1, are provided by the stromal tumor microenvironment." (PMID 24965524, 2014). "CCN1-dependent signaling pathways were not involved mechanistically in this pro-myeloma effect as no alterations in phosphorylated p38, ERK1/2, and STAT3 by CCN1 treatment of INA-6 cells was observed." (PMID 24965524, 2014).
endometriosis (4 papers, 2006 to 2020). The growth of functional endometrial tissue in anatomic sites outside the uterine body. "Repeated genes from the MS-phase (CCN1, CRISP3, EGR1, FOS, FOSB, and TRPM6) could be associated with affected receptivity in endometriosis." (PMID 32474803, 2020).
gastric adenocarcinoma (4 papers, 2007 to 2020). "The overall survival rate was significantly higher in those with low expression of CCN1 compared to that in the high expression group among lung squamous cell carcinoma (LUSC) as well as bladder urothelial cancer (BLCA) and stomach adenocarcinoma (STAD) patients." (PMID 31429823, 2019).
idiopathic pulmonary fibrosis (4 papers, 2022 to 2024). Idiopathic pulmonary fibrosis (IPF) is a nonneoplastic pulmonary disease that is characterized by the formation of scar tissue within the lungs in the absence of any known cause. "Its expression changes in response to endogenous factors and external stimuli, such as oxidative stress, mechanical stress, and ultraviolet irradiation, and aberrant CCN1 expression is associated with aging and age-related diseases, including idiopathic pulmonary fibrosis (IPF) and OA." (PMID 38928297, 2024).
oral squamous cell carcinoma (4 papers, 2012 to 2025). "In oral squamous cell carcinoma (SCC), in vitro overexpression of CCN1/Cyr61 appears to regulate the invasive phenotype of these cells, and increased expression of CCN1 in human biopsies of oral SCC correlated with poor prognosis of the disease." (PMID 34205668, 2021).
osteoarthritis (4 papers, 2020 to 2024). A noninflammatory degenerative joint disease occurring chiefly in older persons, characterized by degeneration of the articular cartilage, hypertrophy of bone at the margins and changes in the synovial membrane. "In articular cartilage left after the completion of skeletal development, CCN1 and CCN2 are present, even under normal conditions, and are increased by the development of osteoarthritis." (PMID 35955724, 2022). "In particular, CCN1 showed proangiogenic activities in HUVEC cells through binding to αvβ3- and α6β1-integrins, while WISP1 (CCN4) induced IL-6 expression in fibroblasts from synovial membrane from patients with osteoarthritis (OASMFs) through αvβ5-integrin." (PMID 38145300, 2024). "CCN1 and CCN2 are found therein, probably to support the potential to proliferate and supply the cartilaginous ECM, which is, however, insufficient to combat osteoarthritis per se." (PMID 35955724, 2022).
ovarian serous adenocarcinoma (4 papers, 2019 to 2024). An adenocarcinoma that arises from the ovary and is characterized by the presence of malignant epithelial cells that, in well differentiated tumors, resemble the epithelium of the fallopian tube or, in poorly differentiated tumors, show anaplastic features and marked nuclear atypia. "We performed the qRT-PCR analysis of TGFβ components (TGFB1, TGFB2, TGFBR1, TGFBR2), Wnt5A/ROR1/ROR2, and Hippo-related genes (YAP1, TAZ, CCN1, and CCN2) in serous ovarian cancer subtypes (LGSOC, HGSOC, BLSOC) compared to the normal ovary." (PMID 35053353, 2022).
renal fibrosis (4 papers, 2013 to 2022). A final common manifestation of a wide variety of chronic kidney diseases characterized by glomerulosclerosis and tubulointerstitial fibrosis. "Second, the expression of CCN1 was positively correlated with renal fibrosis after AKI indicating that CCN1 was highly related to kidney fibrosis in a long period of time injury." (PMID 33192525, 2020).
viral infection (4 papers, 2020 to 2022). "Connective tissue growth factor/Nephroblastoma overexpressed gene family 1 (CCN1), an important inflammatory factor secreted by astrocytes, is reported to regulate innate immunity and viral infection." (PMID 31957543, 2020). "It is reported that many viral infections can enhance the expression of CCN1." (PMID 35418961, 2022). "However, the mechanism by which astrocyte viral infection affects CCN1 expression remains undefined." (PMID 31957543, 2020).
Barrett esophagus (3 papers, 2012 to 2024). Esophageal lesion lined with columnar metaplastic epithelium which is flat or villiform. "In particular, CCN1 is one of the most highly expressed proteins in the esophageal epithelium and has been associated with various pathological conditions, including ESCC, Barrett's esophagus, and esophageal adenocarcinoma." (PMID 22701179, 2012). "On the contrary, CCN1 promotes CASP3, not only in its transcription but also in its translation and activation, forming the basis for CCN1‐induced esophageal adenocarcinoma cell apoptosis." (PMID 39524140, 2024).
colon adenocarcinoma (3 papers, 2007 to 2025). "Our analysis uncovered a positive correlation between USP52 and YAP1 as well as its targeted genes CCN1 (CYR61) and CCN2 (CTGF) in the TCGA-Colon Adenocarcinoma (COAD) cohort." (PMID 40962058, 2025).
dilated cardiomyopathy (3 papers, 2015 to 2022). Cardiomyopathy which is characterized by dilation and contractile dysfunction of the left and right ventricles. "CCN1 also increases levels of the myocardial apoptotic molecule Fas ligand (FasL), which activates the ERK1/2 pathway, leading to dilated cardiomyopathy and advanced heart failure." (PMID 36687680, 2022).
esophageal cancer (3 papers, 2021 to 2024). A primary or metastatic malignant neoplasm involving the esophagus. "In esophageal cancer, we found that CCN1 promotes ESCC16 while is lethal to EAC." (PMID 39524140, 2024).
fibrosis (3 papers, 2022 to 2025). the formation of excess fibrous connective tissue in an organ or tissue in a reparative or reactive process. "After 5/6 Nx, the myocardial structure of mice was disordered, and cardiac fibrosis was obvious compared to that in WT mice; however, these aberrant changes in cardiac tissues were abolished in CCN1−/− mice or CCN1−/− + CKD mice." (PMID 40225592, 2025). "Apical resection‐induced cardiomyocyte CCN1 secretion results in fibroblast senescence, which enhances the proliferation of cardiomyocytes and decreases cardiac fibrosis to improve neonatal heart regeneration." (PMID 36117396, 2022).
ischemia (3 papers, 2008 to 2021). A hypoperfusion of the BLOOD through an organ or tissue caused by a PATHOLOGIC CONSTRICTION or obstruction of its BLOOD VESSELS, or an absence of BLOOD CIRCULATION. "More recently, the proangiogenic role of CCN1/CYR61 in skeletal muscle was evaluated using a patch containing exogenous CCN1/CYR61 in a rabbit model of trauma with associated ischemia and increased compartmental pressure." (PMID 34063397, 2021). "Consistent with the proangiogenic role of CCN1/CYR61 described in several tissues, its expression through adenoviral infection leads to improved skeletal muscle angiogenesis and blood perfusion, even better than VEGF expression, in a hindlimb rabbit model of ischemia." (PMID 34063397, 2021).
ischemic disease (3 papers, 2017 to 2020). Lack of blood supply to an area of the body, resulting in impairment of tissue oxygenation. "However, despite these advances in our understanding of CCN1 function in vascular biology, the range of CCN1 actions and potential implications in the pathogenesis of ischemic diseases remain unknown." (PMID 28469167, 2017).
leukemia (3 papers, 2014 to 2019). A malignant (clonal) hematologic disorder, involving hematopoietic stem cells and characterized by the presence of primitive or atypical myeloid or lymphoid cells in the bone marrow and the blood. "The inhibition of CCN1 in leukemia cells can inhibit cell growth by inhibiting the activation of the MEK/ERK signaling pathway." (PMID 31427569, 2019). "We analyzed CCN1 expression in seven leukemia cell lines and found the highest levels in two AML lines, U937 and Kasumi-1." (PMID 25187756, 2014). "CCN1 plays distinct roles in various tumor types, but little is known regarding the role of CCN1 in leukemia." (PMID 25187756, 2014). "U937 and Kasumi-1 cells had markedly higher CCN1 expression than the 5 other leukemia cell lines, and CCN1 protein expression was higher in the AML bone marrow samples than in the normal bone marrow samples." (PMID 25187756, 2014). "We analyzed CCN1 protein expression in leukemia cell lines and in AML bone marrow samples." (PMID 25187756, 2014). "Here, we show that CCN1 is expressed in two AML cell lines (U937 and Kasumi-1) and in AML bone marrow samples but not in other leukemia cell lines, such as Jurkat (T-ALL), K562 (CML), CEM (T-ALL) or HL-60 (AML) cells." (PMID 25187756, 2014).
lupus nephritis (3 papers, 2022 to 2025). Glomerulonephritis in the context of systemic lupus erythematosus. "The condition of lupus nephritis (LN) was chosen as the disease model, because the diverse pro-angiogenic, anti-fibrotic, and anti-inflammatory functions of CCN1 are relevant to the complex vascular, fibrotic, and immune pathology of LN." (PMID 40843448, 2025). "High CCN1 expression in MD cells was confirmed in the mouse and human kidney with diminished levels in patients with lupus nephritis." (PMID 40843448, 2025). "CCN1 protein was specifically expressed in MD cells in the human kidney, and its expression was reduced in lupus nephritis (LN) patients which is consistent with recently published results indicating significantly reduced CCN1 mRNA levels in LN and other CKD conditions." (PMID 40843448, 2025). "Compared with living donors, CCN1 was significantly underexpressed in patients with CKD with minimal change disease, thin basement membrane, membranous glomerulonephropathy, IgA nephropathy, lupus nephritis, vasculitis, hypertensive nephropathy, and focal segmental glomerulosclerosis (FSGS)." (PMID 38598837, 2024).
osteoporosis (3 papers, 2015 to 2025). A condition of reduced bone mass, with decreased cortical thickness and a decrease in the number and size of the trabeculae of cancellous bone (but normal chemical composition), resulting in increased fracture incidence. "The results of the study predicted that higher serum levels of CCN1 are associated with an increased risk of osteoporosis in both UK Biobank and FinnGen datasets, while the former also projected a negative association between serum CCN2 and osteoporosis risk." (PMID 40407982, 2025). "Conversely, cysteine-rich protein 61 (CYR61/CCN1) was the sole member that we identified as being associated with an increased risk of osteoporosis (OR = 1.115, 95% CI = 1.022–1.215, P = 0.014)." (PMID 38260127, 2023). "The bisphosphonate, zoledronic acid, originally used for osteoporosis management, is now in clinical trials as a chemotherapeutic drug; it activates FOXO3a and inhibits expression of the proangiogenic factor CCN1." (PMID 25678856, 2015).
peripheral arterial disease (3 papers, 2020 to 2023). A disorder of the arteries supplying the upper and lower extremity and the visceral organs. "Furthermore, circulating CCN1 levels are significantly correlated with the severity of peripheral arterial disease in diabetic patients." (PMID 34458333, 2021).
type 2 diabetes (3 papers, 2020 to 2023). "We report, for the first time, the comparison of the blood CCN1 levels between patients with type 2 diabetes and healthy individuals." (PMID 37334311, 2023). "CCN1 was also significantly induced in the HFD with added type 2 diabetes model, by ~ 1.7-fold compared with Chow." (PMID 35038159, 2022). "Thus, in addition to CCN2, CCN1 and CCN3 may be novel therapeutic targets for NASH combined with type 2 diabetes with fibrosis." (PMID 35038159, 2022).
acute lung injury (2 papers, 2020 to 2023). A condition of lung damage that is characterized by bilateral pulmonary infiltrates (pulmonary edema) rich in neutrophils, and in the absence of clinical heart failure. "Furthermore, in a ventilator-induced lung injury (VILI) model in mice that was developed to mimic the lung-damaging effects of mechanical ventilation in acute lung injury patients, CCN1 expression was found to be upregulated significantly as a stress-activated gene." (PMID 33105556, 2020). "In a model of acute lung injury (ALI), studies have shown that CCN1 overexpression activates Akt and downstream signalling pathways, promotes cell proliferation and protects lung epithelial cells from apoptosis induced by hyperoxia." (PMID 36762748, 2023).
asthma (2 papers, 2023 to 2026). "Collectively, these results highlight the CCN1 axis as a promising therapeutic target for mitigating airway remodeling in asthma." (PMID 41559741, 2026).
benign prostatic hyperplasia (2 papers, 2008 to 2024). A non-cancerous nodular enlargement of the prostate gland. "Previous studies showed that LPA induces CCN1 in stromal and epithelial prostatic cells and that CCN1 is a viable marker for benign prostatic hyperplasia." (PMID 38396744, 2024).
bronchopulmonary dysplasia (2 papers, 2020 to 2023). Bronchopulmonary dysplasia is a chronic respiratory disease that results from complications related to lung injury during the treatment of infant acute respiratory distress syndrome in low-birth-weight premature infants or from abnormal lung development in older infants. "In a model of bronchopulmonary dysplasia (BPD), neonatal rats were treated with recombinant CCN1 protein, and it reduced hyperoxia‐induced lung injury, indicating that CCN1 has an anti‐inflammatory effect." (PMID 36762748, 2023).
cardiomyopathy (2 papers, 2016 to 2025). A disease of the heart muscle or myocardium proper. "Disrupting CCN1/β6β1 engagement abolishes DOX-associated cardiomyopathy in mice." (PMID 27167338, 2016). "We aimed to assess the role of CCN1 in DOX-associated cardiomyopathy." (PMID 27167338, 2016). "Knockin mice expressing an α6β1-binding defective CCN1 mutant (CCN1-DM) became resistant to DOX-induced cardiomyopathy." (PMID 27167338, 2016). "Ccn1dm/dm mice were resistant to DOX-induced cardiomyopathy despite the persistent induction of FasL, demonstrating the essential role of CCN1/α6β1 signaling in DOX cardiotoxicity." (PMID 27167338, 2016). "Disrupting CCN1/α6β1 engagement prevents DOX-induced cardiomyopathy in mice." (PMID 27167338, 2016).